TRIB1 (tribbles pseudokinase 1)
Description:
Adapter protein involved in protein degradation by interacting with COP1 ubiquitin ligase. The COP1-binding motif is masked by autoinhibitory interactions with the protein kinase domain. Serves to alter COP1 substrate specificity by directing the activity of COP1 toward CEBPA. Binds selectively the recognition sequence of CEBPA. Regulates myeloid cell differentiation by altering the expression of CEBPA in a COP1-dependent manner (By similarity). Controls macrophage, eosinophil and neutrophil differentiation via the COP1-binding domain (By similarity). Interacts with MAPK kinases and regulates activation of MAP kinases, but has no kinase activity.
Synonyms: TRB-1; GIG-2; C8FW; GIG2; TRB1; SKIP1
Tractability: Antibody: the Human Protein Atlas places it where antibodies can reach. PROTAC: ubiquitination databases record sites on it; a small molecule that binds it is known.
Gene: Protein-coding gene on chromosome 8 (125,430,358 to 125,438,403, forward strand). Ensembl gene ENSG00000173334.
Subcellular location (Human Protein Atlas): Cytosol; Plasma membrane
Pathways (Reactome):
Signal Transduction: NGF-stimulated transcription
Gene Ontology:
Molecular function: mitogen-activated protein kinase kinase binding; protein binding; protein kinase binding; protein kinase inhibitor activity; RNA polymerase II-specific DNA-binding transcription factor binding; transcription regulator inhibitor activity; ATP binding; protein kinase activity; ubiquitin protein ligase binding; ubiquitin-protein transferase regulator activity; enzyme binding; enzyme regulator activity
Biological process: negative regulation of JNK cascade; negative regulation of lipopolysaccharide-mediated signaling pathway; negative regulation of MAPK cascade; negative regulation of smooth muscle cell migration; negative regulation of smooth muscle cell proliferation; regulation of MAP kinase activity; response to lipopolysaccharide; negative regulation of transcription by RNA polymerase II; positive regulation of proteasomal ubiquitin-dependent protein catabolic process; negative regulation of neutrophil differentiation; positive regulation of eosinophil differentiation; positive regulation of macrophage differentiation; regulation of protein metabolic process
Cellular component: cytoplasm; nucleus; cytosol
Genetic constraint (gnomAD): Loss-of-function variants: 12 observed, 23 expected, observed/expected ratio (o/e) 0.52, 90% interval 0.33 to 0.85. The upper end of that interval is the gene's LOEUF score, 0.85, which puts it in group 3 of 6, group 1 being the genes least tolerant of losing a copy. Missense variants: 448 observed, 431.67 expected, observed/expected ratio (o/e) 1.04, 90% interval 0.96 to 1.12. Synonymous variants: 212 observed, 175.7 expected, observed/expected ratio (o/e) 1.21, 90% interval 1.08 to 1.35.
Homologues: Orthologues: chimpanzee TRIB1 (99% identical), macaque TRIB1 (99% identical), dog TRIB1 (97% identical), pig TRIB1 (97% identical), mouse Trib1 (94% identical), rat Trib1 (92% identical), guinea pig TRIB1 (84% identical), tropical clawed frog trib1 (66% identical), rabbit TRIB1 (52% identical), zebrafish trib1 (52% identical), Drosophila melanogaster trbl (35% identical). Paralogues in human: TRIB2 (55% identical), TRIB3 (43% identical), STK40 (27% identical).
Diseases named in the same sentence as TRIB1 in open-access papers:
TRIB1 is named in the same sentence as 101 diseases in open-access papers, as found by Europe PMC text mining. Sharing a sentence is not in itself a finding about the gene and the disease. The quoted sentences say what the papers report.
prostate carcinoma (19 papers, 2016 to 2025). A carcinoma that arises from epithelial cells of the prostate gland. "TRIB1 overexpression causes increased sphere formation in prostate cancer cell lines and increased tumor formation in a xenograft mouse model." (PMID 38791967, 2024). "TRIB1 influences the prostate cancer tumor microenvironment by causing CD136+ macrophage infiltration, promoting M2 macrophage differentiation, and affecting cytokine secretion by inhibiting IкB-ζ (NF-кB inhibitor zeta)." (PMID 38791967, 2024). "Trib1 induced macrophages to express M2 phenotype markers in prostate cancer, whereas Trib1 deficiency attenuated the expression of M2-marker genes upon IL-4 stimulation." (PMID 32256487, 2020). "Mouse modeling and functional analysis revealed that aberrant TRIB1 expression is causal to prostate cancer pathogenesis." (PMID 32932846, 2020). "TRIB1 is associated with tumorigenesis in acute leukemia and prostate cancer." (PMID 34539875, 2021). "TRIB1 has been reported to be associated with the occurrence and development of a variety of tumors, including leukemia, hepatocellular carcinoma, colorectal cancer, and prostate cancer." (PMID 34589612, 2021). "Additionally miR-132-3p is a potential regulator of TRIB1 in both human and murine macrophages and miR-224-5p has also been already implicated in the regulation of this pseudokinase in prostate cancer." (PMID 33329538, 2020). "Additionally, we found in our KEGG analysis that several miR-132-3p target genes expressed in macrophages, have been suggested to be involved in prostate cancer, a disease in which TRIB1 has been implicated." (PMID 33329538, 2020). "However, TRIB1 has been associated with the development and progression of a number of solid tumour types, including breast cancer, hepatocellular carcinoma, glioma, gastric cancer, prostate cancer and colorectal cancer." (PMID 34205360, 2021). "However, our data supports the hypothesis that the role of TRIB1 in prostate cancer is, at least in part, linked to macrophage polarization and function, as a recent work has suggested." (PMID 33329538, 2020). "Previous reports have indicated that TRIB1 is overexpressed in several cancer types including prostate cancer, lymphoma and, CNS cancers." (PMID 37528172, 2023). "miR-224 was found to be involved in suppressing prostate cancer progression by downregulating the expression of Tribbles homolog 1 (TRIB1)." (PMID 36362044, 2022). "In prostate cancer, the overexpression of TRIB1 promotes cytokine secretion from the tumour cells, which drives the polarisation of M2-like tissue-resident macrophages in the tumour microenvironment." (PMID 34205360, 2021). "It has been revealed that TRIB1 is highly expressed in prostate cancer and follicular thyroid cancer, and promotes the proliferation, survival, and tumor growth of cancer cells." (PMID 34589612, 2021). "Our data demonstrate that modulation of TRIB1 by miRNAs alters the inflammatory profile of both human macrophages and prostate cancer cells." (PMID 33329538, 2020). "In sum, we provide unprecedented evidence for the regulation and function of TRIB1 in prostate cancer." (PMID 32932846, 2020). "Here, we show that the long and conserved 3’untranslated region (3’UTR) of TRIB1 is targeted by miRNAs in macrophage and prostate cancer models." (PMID 33329538, 2020). "We experimentally validated the interaction of the 3’UTR of TRIB1 with miR-101-3p and miR-132-3p in human macrophages and prostate cancer, respectively, showing that they control TRIB1 expression and, in turn, alter the mRNA and protein levels of IL-8." (PMID 33329538, 2020). "The immune checkpoint regulator gene, PD-L1 also increased in both conditions, suggesting a role for TRIB1 in regulating the “immune escape” of prostate cancer." (PMID 33329538, 2020).
prostate carcinoma (continued). "By directly targeting TRIB1, miR-101-3p and miR-132-3p control the inflammatory profile of human primary macrophages and prostate cancer cells, as exemplified by enhancing the expression and secretion of pro-inflammatory chemokine, interleukin-8." (PMID 33329538, 2020). "In fact, Liu and colleagues demonstrated that high levels of TRIB1 in prostate cancer correlate with CD163+ macrophage infiltration." (PMID 33329538, 2020). "Here we show that TRIB1 is among the most robustly upregulated coding genes within the 8q24 amplicon in prostate cancer." (PMID 32932846, 2020). "In fact, miR-224-5p has previously been shown to be downregulated in prostate cancer and to target TRIB1 and inhibit prostate cancer growth in vitro." (PMID 33329538, 2020). "In the present work, we systematically analyzed the post-transcriptional regulation of TRIB1 by miRNAs, with focus on macrophages and prostate cancer models." (PMID 33329538, 2020). "More recently, it was shown that TRIB1 negatively regulates IL-8 secretion by inhibiting IKB-zeta in prostate cancer cells." (PMID 33329538, 2020). "By analyzing the publicly available data, we confirmed a significant over-expression of TRIB1 in prostate cancer compared to other cancer types, and an over-expression in prostate cancerous tissue compared to adjacent benign." (PMID 30337939, 2018). "Since androgens are a key signaling molecule in prostate cancer development and the main current therapeutic target (androgen deprivation therapy), this suggests TRIB1 plays a role in the onset and/or development of the disease." (PMID 30337939, 2018). "In summary, the TRIB1 gene is significantly overexpressed in prostate cancer when compared to other types of cancer and it is upregulated in prostate tumor tissue when compared to adjacent cancer-free cells." (PMID 30337939, 2018). "TRIB1 and cMYC are observed to be co-amplified in prostate cancer as well." (PMID 38791967, 2024). "TRIB1 also supports spheroid cell growth in prostate cancer cells." (PMID 37528172, 2023). "TRIB1-induced M2-like macrophage polarization is inhibited by IKB-zeta in prostate cancer." (PMID 36362044, 2022). "MiR-101 binds to the 3′-UTR of tribbles pseudokinase 1 (TRIB1) mRNA, leading to increased transcription and secretion of interleukin-8 to regulate macrophage 2 differentiation in prostate cancer and control the inflammatory profile of human primary macrophages and prostate cancer cells." (PMID 36497343, 2022). "However, while TRIB1 amplification has been demonstrated in prostate cancer, such amplification in other cancers remains to be demonstrated; it has been shown in an animal model of AML but not in human AML datasets." (PMID 35205759, 2022). "In addition, the miRNAs miR-224 and miR-513b-5p have been shown to act as tumor suppressor by downregulating TRIB1 expression in prostate cancer and retinoblastoma cells, respectively." (PMID 35205759, 2022). "TRIB1 inhibits IKB-zeta in prostate cancer and promotes macrophages to the M2 phenotype 43." (PMID 34539875, 2021). "Thus, TRIB1 can affect both development and chemoresistance in leukaemia; glioma; and breast, lung and prostate cancers." (PMID 34205360, 2021). "In addition, they showed that TRIB1 inhibits the secretion of cytokines from prostate cancer cells via inhibition of IKB-zeta." (PMID 33329538, 2020). "A significant number of miRNAs predicted to regulate TRIB1, are also silenced and/or downregulated in prostate cancer, and therefore may contribute to the elevated expression of this pseudokinase in this cancer." (PMID 33329538, 2020). "Of particular interest, a recent from Carracedo and his colleagues demonstrates a cancer cell-intrinsic role for TRIB1 in prostate cancer by showing that TRIB1 often overexpressed in PCa, and that overexpression of this gene in the prostate epithelium accelerates tumourigenesis in a mouse model." (PMID 33329538, 2020).
prostate carcinoma (continued). "Recently, TRIB1 has also been implicated in the pathogenesis of prostate cancer, where it is often overexpressed, even in the absence of genetic amplification." (PMID 33329538, 2020). "However, we also explored the interaction between miR-132-3p and TRIB1 in the context of prostate cancer." (PMID 33329538, 2020). "Put together, these results suggest that the miR-132-3p/TRIB1 axis may be a regulator of the immunological profile of prostate cancer." (PMID 33329538, 2020). "In addition to miR-132-3p, we identified 20 other miRNAs which are either silenced or downregulated in prostate cancer and also predicted to target TRIB1, with multiple binding sites, including miR-101-3p." (PMID 33329538, 2020). "To address the hypothesis that TRIB1 upregulation occurs as a result of downregulation of endogenous miRNAs, we first assessed the endogenous TRIB1 expression in in vitro models of prostate cancer." (PMID 33329538, 2020). "Additionally, TRIB1 has been reported to be overexpressed in prostate cancer, where it controls the expression of endoplasmic reticulum chaperone proteins and induces M2-macrophage differentiation." (PMID 33329538, 2020). "Recently, it has emerged that TRIB1 is often overexpressed in prostate cancer and is associated with cancer risk, but not with aggressiveness and survival." (PMID 33329538, 2020). "In addition, TRIB1 has also been shown to be downregulated by androgens in LNCaP prostate cancer cells." (PMID 30337939, 2018). "Furthermore, independent clinical studies have reported higher expression of TRIB1 in prostate cancer when compared to other cancers and an up-regulation of the TRIB1 gene in prostate cancer tissue when compared to adjacent cancer-free cells." (PMID 30337939, 2018). "The tribbles homologue 1 gene (TRIB1) has recently shown to have a role in prostate tumorigenesis and data-mining of prostate cancer expression data confirmed clinical significance of TRIB1 in prostate cancer." (PMID 30337939, 2018). "Additionally, we and others have observed a down-regulation of the TTTTG-TRIB1 STR and the TRIB1 gene in LNCaP cells after androgen treatment, supporting a link between TRIB1 and prostate cancer." (PMID 30337939, 2018). "The role of miRNAs in the regulation of TRIB1 expression was suggested previously in a study showing that miR-224 downregulation in prostate cancer may promote tumor progression and poor outcomes through the upregulation of its target TRIB1." (PMID 29176948, 2017). "For example, the genes TRIB1, NR4A1, and NR4A2 are significantly upregulated in prostate cancer and can serve as biomarkers." (PMID 40167331, 2025). "TRIB1 overexpression promotes the secretion of IL8 and CXCL2, among other cytokines, from prostate cancer cells by inhibiting the NF-κB inhibitor IKB-zeta." (PMID 34205360, 2021). "Previous studies have found that TRIB1 is overexpressed in acute myeloid leukemia (AML), prostate cancer, and ovarian cancer and promotes tumor development." (PMID 34539875, 2021). "Next, we used the miRCancer database to download the list of miRNAs reported to be dysregulated in prostate cancer and found that 21 downregulated miRNAs are also predicted to target the 3’UTR of TRIB1, according to TargetScan." (PMID 33329538, 2020). "Thus, we speculate that the downregulation of endogenous miRNAs could, at least in part, account for the elevated expression of TRIB1 in prostate cancer, the causes of which have not been established yet." (PMID 33329538, 2020). "Our predicted NFκB pathway suggested 8 novel genes which were found to be highly down-regulated in lethal prostate cancer and highly functionally related to NFκB, namely ATF3, CXCL2, DUSP5, JUNB, NEDD9, SELE, TRIB1, and ZFP36." (PMID 27078000, 2016). "The TRIB1 gene expression showed a higher expression in prostate cancer tumor when compared to adjacent non-malignant tissue (P = 0.0005)." (PMID 30337939, 2018).
prostate carcinoma (continued). "We used existing expression databases and bioinformatics tools that detect functional STRs lying in differentially expressed genes in prostate cancer by us, whereby we identified a penta-STR within the 3′UTR of the tribbles homologue 1 gene (TRIB1): TTTTG-TRIB1." (PMID 30337939, 2018). "It would be interesting to investigate further the role of these two transcripts in prostate cancer development and if the TTTTG-TRIB1 STR found herein has indeed an effect on TRIB1 mRNA stability, by possibly promoting or interfering in the translation of the mRNA." (PMID 30337939, 2018). "No studies have assessed whether TRIB1 is co-amplified together with cMYC in GC; however, both genes were found to belong to the same amplicon in prostate cancer." (PMID 38254916, 2023). "However, unlike recent papers reporting an oncogenic role of TRIB1 in prostate cancer via regulating macrophage infiltration and inducing M2-like polarization 28, to date no study has examined the TAM-specific tumoral capacity dependence on Trib1 and how this may influence tumor development." (PMID 35664073, 2022). "Importantly for six of the eight candidates, (TRIB1, PCA3, GRHL2, ACTG2, GSN, and MXI1) we were able to confirm the differential expression of the genes that harbor these STRs using a large dataset of prostate cancers compared to adjacent non-malignant cells." (PMID 29203868, 2017).